SMAD4 (SMAD family member 4)
Diseases named in the same sentence as SMAD4 in open-access papers (continued):
Sharing a sentence is not in itself a finding about the gene and the disease.
tumor (continued). "In normal epithelial cells and early-stage neoplasms, SMAD4 functions as a tumor suppressor." (PMID 28423626, 2017). "Moreover, animal studies show that Smad4 inactivation is involved in the malignant transformation of gastrointestinal (GI) adenomas, and, during tumor progression, there are reductions in Smad4 mRNA levels." (PMID 28423626, 2017). "Furthermore, the data indicated that COUP-TFII sequestered SMAD4 from binding to TGFβ-target gene promoters in cells and in tumours containing higher levels of COUP-TFII." (PMID 28859090, 2017). "In the search of prognostic biomarkers that could, e.g., allow a better treatment stratification, the role of the tumor suppressor SMAD4 has already been investigated in several previous studies in PC." (PMID 28534865, 2017). "We focused on SMAD4 because it has a tumor-suppressive role in carcinogenesis." (PMID 28055015, 2017). "The deletion of the SMAD4 gene may lead to tumor angiogenesis and thus increase the metastatic potential of tumor cells." (PMID 29065177, 2017). "Interestingly, the ratio of miR-205 level (Tumor/Normal; T/N) was inversely correlated with the ratio of SMAD4 mRNA levels (T/N) in 52 paired tissues (P = 0.0065)." (PMID 28199217, 2017). "As a Co-Smad of the Smad family, Smad4 was identified as a tumor suppressor gene." (PMID 28199217, 2017). "CSMD1, CDKN2A, NOTCH1, and SMAD4 are known to be tumor-suppressor genes." (PMID 29340043, 2017). "Similar SMAD4-dependent suppression of tumour growth was seen upon FIP200 deletion in A549 cells." (PMID 29146913, 2017). "SMAD4 (DPC4) plays an important role in both tumor suppression and progression." (PMID 28160547, 2017). "Next, we investigated if SENP1 regulates the EMT of tumor cells via controlling SMAD4 expression." (PMID 28417919, 2017). "The present study therefore demonstrates that metabolic reprogramming with increased glycolysis and conversion of glucose into lactate is SMAD4 and hsa-miR-1260a dependent and that tumor cells can transfer the propensity to elevated glycolysis to stromal cells via Exo." (PMID 29156694, 2017). "Indeed, components of the TGFβ pathway such as SMAD4 and the ligand receptor TGFBR2 are encoded by classic tumour suppressor genes, which undergo direct loss-of-function mutation during tumorigenesis in certain cancers." (PMID 29146913, 2017). "For instance, the activity of SMAD4 is highly correlated with tumor metastasis." (PMID 26972162, 2016). "We further examined whether the lymphocyte-induced upregulation of PD-L1 on tumor cells is dependent on Smad4 deletion." (PMID 27835902, 2016). "Our hypothesis is that miR-146-5p contributes to regulate cell migration and invasion through the targeting of SMAD4 in normal and tumor thyroid cell lines." (PMID 26883911, 2016). "To clarify whether Pitx2 is a tumor suppressor in the downstream of TGF-β-Smad4 pathway in PDAC, we firstly detected the Pitx2 levels with or without inhibitors against ERK1/2 (PD98059), p38 (SB202190), TGFβ1-Smads (SB431542), and JNK (SP600125)." (PMID 26848620, 2016). "It is clear that Smad4 exerts a tumor-promoting role in HCC." (PMID 26817584, 2016).
tumor (continued). "The loss of SMAD4 is in line with aberrations that are observed within TGF-b signaling and decreased protein levels could explain the inactivation of the TGF-b tumor suppressive pathway in HNSCC." (PMID 27050151, 2016). "In addition, we found that ectopic expression of Smad4 suppressed the growth, invasion, metastasis, and angiogenesis of NB cells, suggesting the tumor suppressive roles of Smad4 in the progression of NB." (PMID 27595937, 2016). "In order to assess whether tumor growth promotion in sw1990/ RV-miR-301a-3p cells was partly due to the suppression of SMAD4, immunohistochemical analysis of xenograft tumor tissues were performed." (PMID 26019136, 2015). "As expected, phosphorylated Smad2 and Smad4 were detected in the untreated tumors (OVA + tumor)." (PMID 26076663, 2015). "Negative Smad4 IHC labeling was associated with tumor size (P = 0.033), lymph node metastasis (P = 0.014), differentiation (P = 0.022), and pathological stage (P = 0.017)." (PMID 25890228, 2015). "Furthermore, SMAD4 appears to play a key role in the progression of PDA tumorogenesis through effects on the tumor microenvironment." (PMID 26172047, 2015). "Based on the recent understanding of TOB1, a putative role of TOB1 may be associated with tumor suppressor SMAD4 and oncogenic CTNNB-mediated signaling, likely including SMAD4-mediated suppression of AURKA-CTNNB activation." (PMID 26694352, 2015). "Smad4 is a tumor-suppressor gene with a key role in the TGF-β signaling pathway." (PMID 25890228, 2015). "Following association with Smad4, the Smad complexes then translocate to the nuclei, where they activate specific target genes including MMP-9 through cooperative interactions with its DNA and other DNA-binding proteins to control tumor progression." (PMID 25940439, 2015). "A few studies had shown that SMAD4 was more inclined to behave as a tumor suppressor." (PMID 26019136, 2015). "With pbMOO approach, the functional unknown protein OCIAD2 was also enrolled into a signal pathway “TGFβ1- TGFβR1- SMAD2/3- SMAD4- AR-OCIAD2” in tumor and adjacent microenvironment." (PMID 24949437, 2014). "The results might suggest that the exact biology or mechanism of SMAD4 is likely different for divergent tumor types." (PMID 25333693, 2014). "We can also speculate that because of the crucial role of SMAD4 in TGF-β induced transcriptional regulation, even a modest decrease in SMAD4 levels could explain the compromised tumor-suppressive role of TGF-β in HNSCC." (PMID 25275298, 2014). "In this sense, SMAD4 may act as a tumor suppressor, which has been demonstrated by reduced expression of SMAD4 in PCa compared to BPH and normal prostate tissue." (PMID 24708576, 2014). "As a tumor suppressor, Smad4 regulates TGF-β-mediated epithelial cell growth or inhibition." (PMID 24944686, 2014). "Tumor CLN2 contained SMAD4 deletion and a concomitant SMAD4 mutation." (PMID 24943349, 2014). "SMAD4 alterations were observed that may explain the decreased tumor suppressive effect of TGF-β in HNSCC." (PMID 25275298, 2014). "To gain insight into the functional role of SMAD4 loss in PDAC cells, we first selected two SMAD4-deficient PDAC cell lines (AsPC-1 and CFPAC-1) and SMAD4 wild-type PANC-1 cells as the model cell lines in which to study the anti-tumor effects of SMAD4 in human PDAC." (PMID 24625091, 2014). "It has also been proposed that the two oppositional endpoints of TGF-β signaling might be distinguished by loss of Smad4 in tumor tissue, which promotes TGF-β-mediated tumorigenesis, while in parallel abolishing its tumor-suppressive functions." (PMID 25050175, 2014).
tumor (continued). "It is suggested that SMAD4 can function as a tumor suppressor gene in gastrointestinal carcinoma." (PMID 24152489, 2013). "The present data showed that miR-224 had oncogenic effects, including the promotion of CRC cell proliferation, migration and invasion, at least in part by targeting the anti-oncogene SMAD4, highlighting the function of miR-224 in the process of tumor progression." (PMID 24152489, 2013). "Smad4 has been previously demonstrated to be a potent tumor suppressor." (PMID 24386371, 2013). "SMAD4 is also a major tumor suppressor which is generally downregulated in cancers." (PMID 24688641, 2012). "Thus, it is possible that Smad4 mediates the tumor inhibitory action of TGF-β signaling, mainly in the progressive stage of tumorigenesis." (PMID 22943793, 2012). "However, Smad4 also has a TGF-β-independent function as a tumour suppressor cooperating with β-catenin/Lef to regulate target gene expression." (PMID 21772334, 2011). "Our results confirm that SMAD4 is downregulated during tumor progression." (PMID 21791112, 2011). "Deletion or degradation of SMAD4 in tumors could specifically inhibit the tumor suppressor effect of TGF-β." (PMID 21791112, 2011). "However, the re-expression of Smad4 in SW480 cells was sufficient to suppress tumor growth in vivo confirming that these cells provide an adequate model to investigate Smad4 tumor suppressor function." (PMID 21492476, 2011). "Smad4 is the common mediator of the tumor suppressive functions of TGF-beta." (PMID 22195733, 2011). "This indicates that haploid insufficiency of Smad4, conferring a 50% of Smad4 protein reduction, could be sufficient to promote tumor formation." (PMID 22204491, 2011). "We have recently identified laminin-332 as a target structure of the tumor suppressor Smad4." (PMID 20307265, 2010). "However, the remaining 10 coding exons (mouse SMAD4 has 11 coding exons with a total of 1,656 bases) were sequenced successfully with all tumor and normal samples." (PMID 20707908, 2010). "We examined exon 7 (with which sequencing succeeded on most normal samples but failed on the tumors) and exon 4 (with which sequencing succeeded on all tumor/normal samples and no mutation was found) of SMAD4." (PMID 20707908, 2010). "Smad4 is a central component of the TGF-β pathway, and degradation of Smad4 in tumors could specifically inhibit the tumor suppressor effect of TGF-β." (PMID 19671175, 2009). "The high frequency of Smad4 mutations in human tumors suggests a role for Smad4 as a tumor suppressor independent of TGF-β signaling." (PMID 19943940, 2009). "Thus, our finding that the tumor and invasion suppressor Smad4 can act as a positive regulator of LM-332 is consistent with current knowledge." (PMID 18664273, 2008). "Thus, it will be interesting in the future to address the impact of the Smad4 status of tumor cells on transcriptional responses in the context of various environmental stimuli." (PMID 18664273, 2008). "However, bona fide haploinsufficiency has been demonstrated for a subset of tumor suppressor loci including SMAD4, an intracellular mediator of the TGF-β and BMP signal transduction pathways." (PMID 19014666, 2008). "Out of 13 polyps analyzed, three (23%) revealed a homogeneously negative staining of the epithelial tumor cells, thus indicating functional loss of the wild-type SMAD4 allele." (PMID 19014666, 2008).
tumor (continued). "Laminin-332 (laminin-5), a heterotrimeric BM component composed of α3-, β3- and γ2-chains, has recently been identified as a target structure of Smad4 and represents the first example for expression control of an essential BM component by a tumor and invasion suppressor." (PMID 18664273, 2008). "Using this approach we could proof Smad4's tumor suppressor function and could identify Smad4 target genes, among them VEGF and E-cadherin." (PMID 18664273, 2008). "Moreover, Dukes C tumours with SMAD4 expression show a significantly longer disease-free survival and significantly more benefit from 5-fluorouracil-based chemotherapy." (PMID 17407575, 2007). "Using this system, we found that reduced tumour growth in vivo could be mediated through physiological as well as excessive levels of Smad4." (PMID 17997817, 2007). "Concurrent with the identification of Smad4 as a tumour suppressor gene, the hypothesis was raised that loss of TGF-β antiproliferative and proapoptotic responses underlie the tumour suppressor function of Smad4." (PMID 17997817, 2007). "Consequently, the outcome of Smad4 reexpression on expression profiles of tumour cells in vivo will widely differ from expression patterns in vitro." (PMID 17997817, 2007). "Thus, physiological Smad4 levels in this cell model are adequate to significantly reduce tumor growth." (PMID 17997817, 2007). "SMAD4 (18q21.1) has been reported to be deleted or inactivated in about 50% of PDACs and, therefore, it is considered to be one of the most likely candidate tumour suppressor genes at this locus." (PMID 17242705, 2007). "However, in all the previous reports discussing the correlation of Smad4 protein and 18q deletion with survival, tumour depth, lymph node metastasis and tumour differentiations were not matched." (PMID 17088901, 2006). "Smad4, a co-Smad of Smad2, is known as a tumour-suppressor gene in different cancer types." (PMID 12569386, 2003). "Smad4 is a candidate tumour-suppressor gene identified recently on chromosome 18q21.1." (PMID 12569386, 2003). "Furthermore, it is possible that some of our tumours had large intragenetic deletions of Smad4, which would have been missed with the detection method used." (PMID 12569386, 2003). "Finally, the reduction in NK cells, which typically play anti-tumor roles, as well as changes in macrophage and neutrophil phenotype and abundance may also contribute to the faster progression of Smad4-deleted PDAC." (PMID 39841099, 2025). "Additionally, an OSCC cell model with and without Smad4 mutation was used to investigate tumor phenotypes, including proliferation and invasion, in relation to EMT markers." (PMID 40507242, 2025). "Moreover, SMAD4 loss was not sufficient to drive an increase in KvPC organoid proliferation in vitro, suggesting that the increase in tumor growth in vivo is mediated by changes in the TME and their crosstalk with malignant cells." (PMID 39841099, 2025). "Furthermore, SMAD4 (chromosome 18q) was deleted in tumor tissues from patients S425 and S028." (PMID 41301905, 2025). "Therefore, p57 is a crucial component of Smad4’s tumor-suppressive program in the liver." (PMID 40999053, 2025). "Therefore, we speculated that SMAD4 plays a tumor suppressive role by upregulating ARHGAP10 expression and further inhibiting the PI3K/AKT/HK2 pathway." (PMID 38230565, 2024). "SMAD4 gene mutations may disrupt the normal functioning of the TGF‐β signaling pathway, causing cells to lose their growth‐inhibitory response and thereby promoting tumor development." (PMID 39162366, 2024). "Furthermore, patients with high Smad4 expression had a significantly larger tumor diameter." (PMID 39346534, 2024).
tumor (continued). "Consequently, the function of Smad4 in regulating tumor progression may be dependent on tumor type, cell type and TEM." (PMID 39346534, 2024). "These opposite effects might be attributed to the baseline T-cell density, immunogenicity, stromal composition, genetic factors including Smad4 deficiency, the effect of TGF-β blockade on the reovirus-induced T-cell influx into the tumor, or the effect of reovirus administration on TGF-β signaling." (PMID 36860656, 2023). "Additionally, these findings indicate SMAD4 has a direct role in suppressing serrated tumor invasion, and that SMAD4 regulatory targets may shape the tumor extracellular environment, revealing an underappreciated role of SMAD4 in tumor invasion suppression." (PMID 38136364, 2023). "Additionally, increased miR-431 could prompt ototoxicity via altering the role of TGF-β/SMAD4 in acid extrusion from the VS tumor." (PMID 37885485, 2023). "For instance, the loss of SMAD4 in intestinal epithelial cells has been shown to result in the upregulation of chemotactic factors, including Ccl9, CCL15, or CXCL1/8, and thereby induces the recruitment of tumor promoting myeloid-derived cells or tumor-associated neutrophils." (PMID 37190048, 2023). "The absence of TAp73 and, as a consequence, loss of expression of Smad4 and biglycan led to activation of TGF-β signaling through Smad independent pathway(s), i.e., ERK1/2, favoring oncogenic TGF-β effects and epithelial-mesenchymal transition (EMT) in the tumor cells of TAp73−/− mice." (PMID 37568607, 2023). "The TGF-β/SMAD4 signaling pathway controls signal transduction from the cell membrane to the nucleus and is involved in many cellular processes such as cell proliferation, migration/motility, differentiation, apoptosis, inflammatory/immune response, and tumor formation and progression." (PMID 37885485, 2023). "In our study, we could not analyze the association between TRS and SMAD4 status due to the small number of patients (n = 3) who presented almost complete tumor response (CAP1 score)." (PMID 37568581, 2023). "C707 harbors a SMAD4 mutation that renders the tumor cells insensitive to TGF-β signaling pathway disruption, lending credence to the hypothesis that the effect of galunisertib treatment we observe on the tumor is through the tumor-associated stroma." (PMID 36481562, 2023). "We could not evaluate the association between SMAD4 status and tumor regression scores as the statistical conditions to conduct the statistical test were not met." (PMID 37568581, 2023). "Hence, TAp73 in suppressing EMT and cell motility might have implications for other tumor-suppressive functions, e.g., responsiveness to SMAD4-dependent cell death after TGF-β treatment." (PMID 37568607, 2023). "However, whether the exact mechanisms of tumor immune escape and SMAD4-mediated activation or inhibition occur is unclear, which needs further investigation." (PMID 36127339, 2022). "In light of our findings, a possible explanation for this could be that SMAD4mut tumors on the one hand escape the tumor-suppressive function of TGFβ signaling, while on the other hand they retain the potential to become metastatic and therapy-resistant by undergoing SMAD4-independent EMT." (PMID 34857888, 2022). "Our findings may reveal a potential combination therapy for overcoming resistance of PDAC mediated by SMAD4, which paves the way toward a long-sought tumor suppressor reactivation approach and lays the foundation for future precision medicine as the first step." (PMID 36127339, 2022).